NLRP2B (NLR family pyrin domain containing 2B)
Description:
May function as a negative regulator of NF-kappa-B by preventing RELA/p65 phosphorylation at 'Ser-536', thereby inhibiting its transcriptional activity. Through NF-kappa-B regulation may control cytokine release upon Toll-like receptors activation and therefore play a role in modulation of innate immunity. May also play a role in cell cycle progression and apoptotic process.
Synonyms: CLRX.1; NLRP2P; NOD24; POP4; NALP2P
Tractability: No criterion of Open Targets' tractability assessment is met for any kind of drug.
Gene: Protein-coding gene on chromosome X (57,677,067 to 57,680,260, reverse strand). Ensembl gene ENSG00000215174.
Subcellular location: Cytoplasm; Nucleus
Gene Ontology:
Biological process: negative regulation of cell cycle; negative regulation of interleukin-1 beta production; negative regulation of NLRP3 inflammasome complex assembly; negative regulation of peptidyl-serine phosphorylation; negative regulation of toll-like receptor signaling pathway; negative regulation of tumor necrosis factor-mediated signaling pathway; positive regulation of apoptotic process
Cellular component: cytoplasm; nucleus
Homologues: Orthologues: pig NLRP2B (58% identical).
Diseases named in the same sentence as NLRP2B in open-access papers:
NLRP2B is named in the same sentence as 1 disease in open-access papers, as found by Europe PMC text mining. Sharing a sentence is not in itself a finding about the gene and the disease.
NLRP2B shares sentences with these, for which no sentence is quoted: cyst (1 paper).